CEBPB (CCAAT enhancer binding protein beta)
Diseases named in the same sentence as CEBPB in open-access papers (continued):
Sharing a sentence is not in itself a finding about the gene and the disease.
ovarian carcinoma (26 papers, 2013 to 2025). A malignant neoplasm originating from the surface ovarian epithelium. "For instance, SLC16A3, mediated by LINC00035/CCAAT enhancer binding protein beta (CEBPB), enhanced the glycolysis and promoted the development of ovarian cancer." (PMID 36768316, 2023). "Among these TFs, CEBPB, which was upregulated in ovarian cancer, was most significantly correlated with increased H3K79 methylation (P = 1 × 10−86)." (PMID 29712898, 2018). "CEBPB could also promote the transcription of SLC16A3 to help the progression of ovarian cancer." (PMID 38007473, 2023). "However, CEBPB mRNA was significantly increased in ovarian cancer, and there was a positive correlation between C/EBPβ mRNA and protein levels among cell lines and clinical specimens, indicating the involvement of transcriptional regulation of C/EBPβ." (PMID 29712898, 2018). "A subsequent study showed that DAXX promotes ovarian cancer ascites cell proliferation by activating the ERK pathway and directly binding to CCAAT enhancer binding protein-beta (CEBP-β)." (PMID 35087762, 2021). "Though CAAs can modulate ovarian cancer metastasis, studies also reported that ovarian cancer can induce CAA formation via activating the TGF-β1/SMAD3/TRIB3 pathway in reverse, which suppresses the phosphorylation of CEBPβ." (PMID 40709184, 2025). "Studies have shown that under the transcription of CEBPB, long-coded RNA LOC102724169 can enhance cisplatin on the therapeutic effect of ovarian cancer cells (Lynch and May." (PMID 36147496, 2022).
diabetes (24 papers, 2010 to 2025). "Among them, CEBPA and CEBPB are adipogenic transcription factors that not only impact adipogenesis but also influence the occurrence of diabetes." (PMID 39553470, 2024). "Suppression of endogenous IGF-1 in diabetes may contribute to neuropathy and its upregulation at the transcriptional level by CEBPβ can be a promising therapeutic approach." (PMID 35298717, 2022).
gastric cancer (23 papers, 2012 to 2026). A primary or metastatic malignant neoplasm involving the stomach. "This promotes the formation of the PGC1α/CEBPB transcriptional complex, which transcriptionally induces carnitine palmitoyltransferase 1, thereby enhancing fatty acid oxidation and driving gastric cancer progression." (PMID 40978035, 2025). "Overexpression of DDIT3 promotes stemness of cancer stem cells in gastric cancer by regulating CEBPβ." (PMID 38474084, 2024). "CEBPB is involved in transcriptional up-regulation of SphK1 by LPA in gastric cancers." (PMID 24597747, 2014). "In addition, DDIT3 promotes cancer stem cell stemness by upregulating CEBPβ in gastric cancer." (PMID 37371530, 2023). "In a study on gastric cancer, it was shown that DDIT3 can directly upregulate the transcription factor CEBPB, thereby increasing the stemness of gastric cancer cells and the expression of stem cell markers: SOX2, NANOG, OCT4, and CD133." (PMID 38710698, 2024).
leukemia (23 papers, 2012 to 2024). A malignant (clonal) hematologic disorder, involving hematopoietic stem cells and characterized by the presence of primitive or atypical myeloid or lymphoid cells in the bone marrow and the blood. "This identified top 10 TFs involving in hematopoietic cells proliferation and differentiation (SPIB, ATF4) and pathogenesis of leukemia (CEBPB, CTCF)." (PMID 38693103, 2024). "The abnormal translation of CEBPB has been widely reported in macrophage migration, metabolic diseases and leukemia." (PMID 35459206, 2022). "In keeping with this, CIMP leukemias also exhibited increased methylation at NOTCH1, MYB, and TAL1 binding sites than ETP-ALL, and hypomethylation of TFBS for myeloid master regulators such as CEBPA, CEBPB, and SPI1." (PMID 38972954, 2024). "Furthermore, the ChIP-seq read counts of CEBPB in the peak regions of STAT1 are correlated (with r > 0.3) in lymphoblastoid (GM12878) and in leukemia (K562) cell lines." (PMID 30142147, 2018).
lung carcinoma (20 papers, 2010 to 2026). "However, the role of CEBPB in lung cancer is quite controversial, possibly because the function of CEBPB depends on the transcription factors cooperating in each cellular environment." (PMID 38710698, 2024). "Our findings revealed that in lung cancer tissues or cells, five transcription factors—FOXA1, CEBPB, CTCF, LMNB1, and POLR2A—concurrently regulate the transcription of COL5A1, MMP1, and SERPINE1." (PMID 39551792, 2024). "In a study on non-small cell lung cancer, the drug resistance of NRF2-activated lung cancer was achieved through the cooperative function of NRF2 and CEBPB." (PMID 38710698, 2024). "Some studies have found that drug resistance to lung cancer is achieved through the synergistic effect of NRF2 and CEBPB." (PMID 36613925, 2022). "Expression of CEBPB was not altered in human lung cancer samples." (PMID 25767874, 2015).
colon carcinoma (18 papers, 2010 to 2025). "The inhibition of CEBPB mitigated the inflammation-driven carcinogenic effects associated with AOM/DSS, indicating that CEBPB facilitates the progression from colitis to colon cancer." (PMID 40487290, 2025). "Furthermore, we identified numerous CTS transcriptional signatures whose expression was significantly associated with prognosis in colon cancer, such as CEBPB, PPARGC1, STAT3, MTOR, BCL2, JAK2, and CDK1." (PMID 31186640, 2019). "CEBPB has been shown to promote the invasion of colon cancer cells." (PMID 40487290, 2025). "In summary, our results suggest that CEBPB facilitates the progression of UCCRC by activating the NF-κB/STAT3 signaling cascade, thereby contributing to a better understanding of the mechanisms underlying the progression from colitis to colon cancer." (PMID 40487290, 2025). "Interestingly, we found that many of the DEGs and their regulators were prognostic markers for colon cancer, including CEBPB, PPARGC1, STAT3, MTOR, BCL2, JAK2, and CDK1." (PMID 31186640, 2019). "These transcriptional signatures are mainly involved in immune regulation (CEBPB, STAT3, and JAK2), metabolism (PPARGC1 and MTOR), cell cycle (CDK1), and apoptosis (BCL2), suggesting that the deregulation of these pathways in CTS may contribute to the altered prognosis in colon cancer." (PMID 31186640, 2019). "For example, the expression of CEBPB, a gene significantly upregulated in CTS and a hub node in the PPI network, had a significant negative correlation with OS in colon cancer." (PMID 31186640, 2019).
prostate carcinoma (17 papers, 2010 to 2025). A carcinoma that arises from epithelial cells of the prostate gland. "In another study, CEBPB enhances autophagy in prostate cancer cells by promoting autophagosome-lysosome fusion and inducing REDD1 expression, whereas its downregulation increases prostate cancer cell sensitivity to bortezomib." (PMID 40406488, 2025). "RNA-seq data show high levels of CEBPB transcripts in multiple prostate tissue cell lines and a marked anti-correlation with AR levels in human prostate cancers (N = 319, P = 8e-18 Pearson correlation)." (PMID 28663546, 2017). "In fact, apart from CLU, also CEBPB and D seem to play a role in PC proliferation, as interleukin-6 (IL-6) treatment increases the expression of CEBP-D family member, inducing IL-6/STAT3-dependent growth arrest on prostate cancer cells in vitro." (PMID 29562723, 2018).
Sepsis (17 papers, 2017 to 2026). Sepsis is defined as life-threatening organ dysfunction caused by a dysregulated host response to infection. "This research demonstrates the impact of IBD on the progression of Sepsis and analyses two DEGs, BCL2A1 and CEBPB, as potential diagnostic biomarkers for both IBD and Sepsis." (PMID 39993996, 2025). "BCL2A1 and CEBPB expression levels were significantly increased in mice with Sepsis complicated by IBD." (PMID 39993996, 2025). "To explore the mRNA expression levels of BCL2A1 and CEBPB, we consulted datasets from healthy individuals as well as patients with Sepsis and IBD." (PMID 39993996, 2025). "We also demonstrated that FoxO1 directly bind to CEBPB in macrophages following LPS stimulation, revealing the complex molecular regulatory network in which FoxO1 acts as a pivotal transcription factor in sepsis." (PMID 41362741, 2026). "In addition, CEBPB has recently been identified as a key immune‐related gene in sepsis patients and a potential therapeutic target for the prevention of liver failure in sepsis patients." (PMID 39993996, 2025). "Additionally, the ROC analysis confirmed that the expression of BCL2A1 and CEBPB were of great diagnostic value in IBD and Sepsis and." (PMID 39993996, 2025). "BCL2A1 and CEBPB were identified as potential biomarkers with diagnostic value of IBD and Sepsis." (PMID 39993996, 2025). "Furthermore, we confirmed that levels of BCL2A1 and CEBPB were elevated in mice with IBD complicated by Sepsis through real‐time PCR and observed that IBD exacerbates the progression of Sepsis." (PMID 39993996, 2025). "The conditional deletion of Cebpβ in myeloid cells reversed the development of MDSCs during sepsis." (PMID 31129755, 2019). "Finally, it remains to be explored whether BCL2A1 and CEBPB can be incorporated into existing diagnostic protocols as potential biomarkers for both IBD and Sepsis, with the aim of improving disease detection and prognosis." (PMID 39993996, 2025). "Moreover, CEBPB and has-miR-150 might function in neonatal sepsis separately through targeting MAPK14 and BCL11B in the regulatory networks." (PMID 30497506, 2018). "A mouse model of IBD combined with Sepsis was constructed, and real‐time PCR and western blot validated the expression of BCL2A1 and CEBPB." (PMID 39993996, 2025). "These transcription factors (such as CEBPB and ETV6) and miRNAs are potential targets for the treatment of sepsis." (PMID 33032623, 2020). "Therefore, we hypothesise that BCL2A1 ASOs or CEBPB ASOs can influence the progression of Sepsis by targeting BCL2A1 and CEBPB in the intestines of mice." (PMID 39993996, 2025). "In sepsis, RELA, CEBPB, NFKBIA, STAT6, IRF8 and SPI1 were downregulated, with no significant change in NFKB1, JUN and GLI1." (PMID 39444551, 2024).
acute myeloid leukemia (14 papers, 2016 to 2024). Acute myeloid leukemia (AML) is a group of neoplasms arising from precursor cells committed to the myeloid cell-line differentiation. "The differentially expressed transcripts and proteins, predicted transcriptional factors, and key molecules such as HIC1, CEBPB, LYN, and PARP1 may be considered as potential targets for differentiation therapy of acute myeloid leukemia." (PMID 34207065, 2021). "In this study, we show that in acute myeloid leukemia (AML) cells, high expression of vitamin D receptor gene (VDR) is needed for strong and sustained upregulation of CEBPB gene, while the moderate expression of VDR is sufficient for upregulation of CEBPD in response to 1,25D." (PMID 29966306, 2018).
atherosclerosis (14 papers, 2014 to 2026). A disease characterized by the build-up of fatty material and calcium deposition in the arterial wall resulting in partial or complete occlusion of the arterial lumen. "Elevated CEBPB levels are linked to vascular remodeling and atherosclerosis, suggesting it could be a therapeutic target for cardiovascular diseases like vascular inflammation." (PMID 41306918, 2025). "CEBPB inactivation regulates the formation of macrophage foam cells in atherosclerosis by reducing inflammation, endoplasmic reticulum stress, and apoptosis and promoting autophagy." (PMID 35204186, 2022). "Additionally, the silencing of CEBPB was found to trigger anti-inflammatory M2-like polarization and inhibit foam cell formation in a mouse model of atherosclerosis." (PMID 36830768, 2023). "Our results show that AG may regulate NF-κB/CEBPB/PPARG signalling to play a therapeutic role in atherosclerosis." (PMID 35543243, 2022). "AG may regulate NF-κB/CEBPB/PPARG signaling to alleviate atherosclerosis." (PMID 35543243, 2022). "Among them, ANXA2, ApoA1, PGK1, CEBPB and MAP3K3 were related to atherosclerosis and cerebral inflammation." (PMID 34295249, 2021).
Insulin resistance (14 papers, 2012 to 2025). Increased resistance towards insulin, that is, diminished effectiveness of insulin in reducing blood glucose levels. "Downregulation of circulating miR-155 is associated with insulin resistance, poor glycemic control, and increased MetS-related cardiometabolic risk, and these effects are potentially mediated by interaction with CEBPB." (PMID 33540559, 2021). "Functional enrichment analysis showed that SOCS3, IL6, FOXO1, CEBPB, SOX9, and PPARGC1A were mainly involved in the adipocytokine signaling pathway, insulin resistance, FoxO signaling pathway, AMPK signaling pathway, and PI3K-Akt signaling pathway." (PMID 38415055, 2024). "In this study, obese patients with insulin resistance (high HOMA-IR) showed reduced miR-155 and increased CEBPB expression in peripheral blood." (PMID 33540559, 2021). "We could find a significant difference of CEBPB gene methylation between PCOS-NIR and PCOS-IR patients (p = 0.00017), suggesting CEBPB involving in insulin resistance in PCOS patients." (PMID 23705014, 2013). "Analysis of the target genes revealed that CEBPB, but not KRAS, and SOCS1 was upregulated in obese patients MetS and insulin resistance." (PMID 33540559, 2021).
melanoma (14 papers, 2016 to 2026). A malignant, usually aggressive tumor composed of atypical, neoplastic melanocytes. "A few studies have also reported potential associations between CEBPB and metastasis or treatment response in melanoma." (PMID 36353635, 2022). "In addition, among the miRNAs targeting CEBPB, hsa-miR-20b-5p has been implicated in atrial fibrillation and liver cirrhosis, and hsa-miR-106b-5p is known to contribute to the progression of pulmonary arterial hypertension and melanoma." (PMID 41007174, 2025). "The results revealed that the CSTB, GBF1, TYR, RAC1, SLC2A1 and NOTCH3-coding proteins were significantly enriched in melanoma samples, while CEBPB-coding protein had low expression in melanoma samples." (PMID 37217516, 2023). "First of all, the conclusion about the influence of CEBPB on the tumor microenvironment of melanoma patients was mainly based on the prediction of the immune cell infiltration ratio in tumor tissues." (PMID 36353635, 2022). "To explore if CEBPB has any influence on melanoma proliferation, we overexpressed CEBPB in both A375 and SK-MEL-2 cell lines and performed a CCK-8 assay." (PMID 36353635, 2022). "To validate the downregulation of CEBPB in melanoma, we performed RT-PCR of CEBPB in dermal fibroblast from the normal skin of a keloid patient and A375 and SK-MEL-2 melanoma cells." (PMID 36353635, 2022). "In a study published in 2021, researchers show that the level of the lncRNA PTENP1-AS is promoted by the transcription factor CCAAT/enhancer binding protein beta (CEBPB) transcription factor in melanoma cell lines that are resistant to B-Raf proto-oncogene, serine/threonine kinase (BRAF) inhibitors." (PMID 41362671, 2026). "CEBPB therefore might affect the initiation and progression of melanoma through the modulation of the tumor microenvironment rather than the malignant cell itself." (PMID 36353635, 2022). "In addition, the CEBPB mRNA level was significantly lower in melanoma cells than in normal dermal fibroblasts." (PMID 36353635, 2022). "As with thapsigargin, WX8 induced PERK‐dependent phosphorylation of EIF2A protein and upregulation of ATF4 and DDIT3 proteins in melanoma A375 cells accompanied by translocation of transcription factors ATF4 and CEBPb to the nucleus." (PMID 38414326, 2024). "Five of nine identified ER stress-related genes, CEBPB, TYR, SLC2A1, NOTCH3 and RAC1, have been reported to engage in melanoma malignant behavior regulation." (PMID 37217516, 2023). "In contrast, CEBPB overexpression almost had no influence on the proliferation ability of melanoma cells." (PMID 36353635, 2022). "Another limitation of this study was the lack of normal melanocytes for validation of CEBPB mRNA level, which was superseded by dermal fibroblast, although the CEBPB expression was indeed very low in A375 and SK-MEL-2 melanoma cells." (PMID 36353635, 2022).
neuroblastoma (12 papers, 2011 to 2023). Neuroblastoma (NB) is the most common solid, extracranial childhood tumor. "Additionally, we evaluated the microarray dataset GSE1825 from the GEO database for CEBPB expression in Ewing sarcoma patient samples compared to neuroblastoma patient samples and found significantly higher CEBPB expression in the Ewing sarcoma samples (P = 0.016)." (PMID 28148901, 2017). "Recent studies have identified the transcription factors CEBPB and CEBPD as CP-dn-ATF5 targets, suggesting they are also potential targets for neuroblastoma." (PMID 38014922, 2023).
steatosis (12 papers, 2015 to 2025). Increased lipid within the cytoplasm of cells. "CEBPB not only facilitates viral transcription but also contributes to HCC cell proliferation and invasion and predating pathogenic events subsuming inflammation, endoplasmic reticulum stress and hepatic steatosis when highly expressed." (PMID 32784555, 2020). "In addition, this treatment seemed to play the role of metabolic protection being capable to restore the normal level of genes expression upregulated after steatosis treatment, between them RXRA, NR1H2, CEBPB, ADIPOR2, and CYP2E1." (PMID 36770927, 2023).
cardiac hypertrophy (11 papers, 2020 to 2024). "CEBPB is involved in exercise-induced cardiac hypertrophy and a protective pathway against pathological cardiac remodeling." (PMID 36139449, 2022). "We also examined levels of CCAAT/enhancer-binding protein beta-2 isoform (CEBPβ), a DNA-binding transcription factor linked to cell proliferation, differentiation, and non-pathologic cardiac hypertrophy." (PMID 37237932, 2023).
Parkinson disease (11 papers, 2017 to 2025). A progressive degenerative disorder of the central nervous system characterized by loss of dopamine producing neurons in the substantia nigra and the presence of Lewy bodies in the substantia nigra and locus coeruleus. "Previous research demonstrated that NR1H4 exerts neuroprotective effects in Parkinson’s disease by suppressing astrocyte activation and neuroinflammation via the CEBPβ/NF-κB pathway." (PMID 41472140, 2025). "Inhibition of CEBPβ ameliorates glial activation and the neuroinflammatory response in a rat model of Parkinson’s disease." (PMID 35393391, 2022). "It has been demonstrated that silencing CEBPβ alleviates glial activation and reduces dopaminergic damage in a Parkinson’s disease model." (PMID 35393391, 2022).